TRIM25 (tripartite motif containing 25)
Diseases named in the same sentence as TRIM25 in open-access papers (continued):
Sharing a sentence is not in itself a finding about the gene and the disease.
cancer (54 papers, 2016 to 2025). A tumor composed of atypical neoplastic, often pleomorphic cells that invade other tissues. "Several recent reviews have focused on the roles of TRIM25 and its underlying mechanisms in cancer and inflammatory diseases." (PMID 40431746, 2025). "At the same time, a reporter assay conducted in HEC-1A and Ishikawa cells showed that TRIM25 induced the transcriptional activity of NF-κB, whose deregulation is linked to the malignant progression of a large number of cancers, including EC." (PMID 34208621, 2021). "Overexpression of APP and TRIM25 in cancer patients was associated with low overall survival and the reverse was true for ELAVL1." (PMID 34193143, 2021). "By unveiling this TRIM25 unexpected function, a novel mechanism of drug resistance in humancolorectal carcinoma cells associated with the activity of TRIM25 as an inhibitor of chemotherapeutic drug-inducedapoptosis was described." (PMID 33961438, 2021). "In this case, however, RBPJ proteolysis appeared to increase malignancy, which may apply for other cancer types linked to TRIM25 activity as well." (PMID 36293193, 2022). "Jang Hyun Choi and colleagues at the Ulsan National Institute of Science and Technology, Korea, have found that TRIM25, a protein implicated in cancer and antiviral immune responses, reduces the activity of PPARγ by adding a small regulatory protein that acts as a signal for degradation." (PMID 30323259, 2018). "Furthermore, TRIM25 plays a role in promoting proliferation of many cancer cell types, often in association with the estrogen response." (PMID 29117863, 2017). "Specifically, targeting the RING subfamily of E3 ubiquitin ligases including TRIM25, which can confer specificity to the ubiquitin machinery, has shown promise against cancer in preclinical and clinical trials and is a widely recognized approach." (PMID 39851496, 2025). "Cross-referencing these candidate proteins with UbiBrowser-predicted E3 ubiquitin ligases, we focused on TRIM25 (tripartite motif-containing 25), which plays a pivotal role in various cancers by inducing ubiquitination." (PMID 41208881, 2025). "Recent studies have revealed novel mechanisms by which TRIM25 regulates cancer cell growth and migration based on its catalytic activity." (PMID 40431746, 2025). "Based on its transcriptional and post-transcriptional regulatory mechanisms, TRIM25 serves as an oncogenic factor promoting the proliferation and migration of cancer cells." (PMID 40431746, 2025). "This targeted mechanism positions N6F11 not only as a promising therapeutic candidate but also as a potential chemical probe for exploring TRIM25-dependent ferroptosis pathways in cancer biology." (PMID 41471274, 2025). "The fact that the Nrf2 pathway is one of prominent cell survival pathways that protect cancer cells from apoptosis inhibition of canonical TRIM25-Keap1-Nrf2 pathway implies another potential strategy for blocking cell survival pathways under chemotherapy." (PMID 39851496, 2025). "These basic biological processes are critical in cancer development, inflammation, and innate immunity, and most of them are related to the E3 ligase activity and RNA-binding ability of TRIM25." (PMID 40431746, 2025). "N6F11 selectively induces ferroptosis in cancer cells in a variety of models by targeting TRIM25-mediated GPX4 degradation in pancreatic cells." (PMID 39359721, 2024). "TRIM25 is an E3 ligase that is involved in adipocyte differentiation and promotes cancer cell growth." (PMID 38183356, 2024). "In contrast N6F11 represents the first cell type-dependent ferroptosis inducer by selectively degrading GPX4 in cancer cells through the action of TRIM25, exhibiting efficacy and safety simultaneously." (PMID 38844964, 2024). "Specifically, TRIM14, TRIM25, TRIM32, TRIM44, TRIM59, and TRIM29 exhibit abnormal expression in different cancer types and have been linked to patient prognosis." (PMID 39273003, 2024).
cancer (continued). "TRIM25 is involved in growth control and metastasis of cancer cells and in the defense against viruses." (PMID 37770115, 2023). "Targeting p300 for degradation puts TRIM25 in the heart of p300 regulation, which makes TRIM25 an interesting target for cancer therapy." (PMID 37770115, 2023). "TRIM25 plays several roles in the cells notably during development and differentiation in cancer and in the innate immune system." (PMID 36232890, 2022). "The E3 ubiquitin ligase TRIM25 has been reported to play important roles in the development of several cancers and innate immunity." (PMID 36171622, 2022). "Since, as we propose here, miR-3614-5p, a product of TRIM25, fine tunes immune response, it will be interesting to study miR-3614-5p expression and function in these cancer contexts." (PMID 35935998, 2022). "When examined in the context of cancer, TRIM25-mediated ubiquitination primarily targets varied proteins for proteolytic degradation, which can either enhance or hinder carcinogenesis." (PMID 36067236, 2022). "Studies revealed that miRNA is capable of playing a critical part in cancer progression by regulating TRIM25." (PMID 33506106, 2021). "TRIM25 regulates other processes such as NF-κB signaling and cancer cell growth, so it would be interesting to see if TRIM25 antagonism affects its role in other pathways that benefit viral replication." (PMID 33925296, 2021). "High expression of TRIM25 has been demonstrated in a variety of cancers, such as CRC, lung cancer, and breast cancer." (PMID 33966039, 2021). "Studies have confirmed that the abnormal expression of TRIM25 is a crucial factor in the development of carcinoma." (PMID 33506106, 2021). "Tripartite motif-containing 25 (TRIM25) has been found to be involved in various carcinomas comprising AML." (PMID 33506106, 2021). "Studies have shown that TRIM25 can be used as a transcription factor to regulate cellular biological processes and exert a carcinogenic function in carcinoma progress." (PMID 33506106, 2021). "Contrary to this, overexpression of some oncogenic TRIMs in various cancers is frequently due to the loss of miR dependent gene suppression as demonstrated—e.g., for TRIM11, TRIM14, TRIM24, TRIM25, and TRIM44." (PMID 33066016, 2020). "Again, this feature is exemplarily highlighted for TRIM25 thus demonstrating the complexity of TRIM25 contribution to cancer." (PMID 33066016, 2020). "For its clinical significance in cancers, we then detected the expression levels of TRIM25, Keap1 and Nrf2 in cancerous and paired adjacent tissues from 90 HCC patients." (PMID 31953436, 2020). "Here, the authors perform an RNAi screen and identify that the deubiquitinase OTUD5 suppresses cancer growth in a TRIM25 dependent manner, which in turn controls the expression of tumour suppressor protein, PML." (PMID 32826889, 2020). "A number of enzymes involved in the ISGylation process, namely E3 ligases (HERC5 and EFP/TRIM25) and USP18 have been shown to be associated with cancers via ISGylation-dependent and -independent mechanisms 15-18." (PMID 32132870, 2020). "Accordingly, an overexpression of TRIM25 has been demonstrated in many human cancers and correlates with a poor prognosis of patients." (PMID 31842382, 2019). "In the past few years, TRIM25 has been found to be abnormally expressed in cancers of the female reproductive system." (PMID 28620119, 2017). "Notably, the role the binding of TRIM25 to mRNAs plays has been described in regard to both cancer therapy and antiviral responses." (PMID 40431746, 2025). "Accordingly, TRIM25 is overexpressed in many human cancers and a high tissue expression level of TRIM25 often correlates with an unfavorable prognosis and outcome of patients, thus highlighting the potential of TRIM25 as a biomarker and a valid therapeutic target for novel anticancer therapies." (PMID 39851496, 2025).
cancer (continued). "Moreover, TRIM25 can target the phosphatase and tensin homolog (PTEN) by mediating its K48- and K63-linked polyubiquitination to enhance PI3K/AKT signaling and cancer cell growth." (PMID 40431746, 2025). "TRIM25 has been shown to play critical roles in various cell death pathways, including apoptosis, pyroptosis, necroptosis, ferroptosis, and autophagy, indicating its potential as a therapeutic target in cancer." (PMID 40431746, 2025). "Additionally, TRIM25 plays pivotal roles in different aspects of tumorigenesis, and data from several laboratories have demonstrated that dysregulated TRIM25 participates in the development of various human cancers." (PMID 39851496, 2025). "Furthermore, N6F11 was identified as a selective ferroptosis inducer that specifically degrades GPX4 via TRIM25-mediated ubiquitination in cancer cells because of its preferential expression." (PMID 40607253, 2025). "This regulation of p300 positions TRIM25 as a putative target for cancer therapy." (PMID 37770115, 2023). "One prime example is TRIM25, which functions in both cancer and antiviral innate immunity." (PMID 36067236, 2022). "In HCC, TRIM25 promotes cancer cell survival and growth through targeting Keap1-Nrf2 pathway." (PMID 33966039, 2021). "Despite extensive research on TRIM25 in cancer, the role of TRIM25 in regulating drug resistance remains largely unknown." (PMID 33966039, 2021). "Interestingly, overexpression of TRIM25 has been reported in several human cancers, including breast, ovarian, prostate, gastric, and lung." (PMID 31842382, 2019). "All these reports indicate that TRIM25 may have worked as a common oncogene in a broad area of cancers." (PMID 28620119, 2017). "Our finding that additional TRIM25 activity controls the stability of short-lived proteins may explain how the FAT10 protein accumulates to a high level in various cancers." (PMID 26996158, 2016). "Similarly, it will be relevant to determine how TRIM25 affects the pathways normally controlled by the proteins and whether this family of proteins is involved in cancer-related inflammation." (PMID 36232890, 2022). "N6F11 activates the E3 ubiquitin ligase tripartite motif containing 25 (TRIM25) to mediate GPX4 degradation and has been shown to be selective for cancer cells." (PMID 40998801, 2025). "Given that TRIM25 is highly expressed in tumor cells but rarely in immune cells, N6F11 can specifically induce ferroptosis in cancer cells while protecting immune cells, thereby avoiding immune suppression side effects." (PMID 41471274, 2025). "In this study, we confirmed the cancer-promoting role of TRIM25 in AML and found that TRIM25 is overexpressed in AML blood samples and cells." (PMID 33506106, 2021). "Because A549 cells are aneuploid cancer cells, we wished to examine the effect of IFIT3 and TRIM25 on Ad replication in normal human cells." (PMID 34724821, 2021). "Additionally, as TRIM25 has been associated to cancer–related pathways, its targeting by E6 may also regulate other functions of this protein that should be addressed in the context of HPV-associated cancer progression." (PMID 32164347, 2020). "It has also been found that IGF2BP3 can stabilize TRIM25, and both TRIM25 and IGF2BP3 play an essential role in cancer cell proliferation." (PMID 32648571, 2020). "TRIM25, a member of the TRIM protein family, is increasingly recognized for its significant impact on a variety of physiological conditions, including innate immunity and cancer 36-38." (PMID 40365288, 2025).
cancer (continued). "Tripartite motif containing 25 (TRIM25) is mainly expressed in cancer cells, but not in immune cells." (PMID 39359721, 2024). "Because TRIM25 is primarily expressed in cancer cells and shows low or no expression in immune cells, N6F11 does not adversely affect the immune system." (PMID 39534872, 2024). "Thereafter, TRIM25 knockdown led to AZGP1 upregulation and induced cancer cell apoptosis." (PMID 38183356, 2024). "A recent study has shown that the compound N6F11 activates tripartite motif containing 25 (TRIM25), which predominantly exists in cancer cells rather than immune cells." (PMID 38844964, 2024). "Thus, this review will focus mainly on the crosstalk of the signaling pathways in cancer development, especially the ones that involve widely studied TRIM proteins, i.e., TRIM28, TRIM25 and TRIM59." (PMID 39451518, 2024). "However, for the same two cancers, when a pathway analysis was run on the shared list of genes whose expression correlates positively with KLLN and TRIM25, the protein ubiquitination pathway was observed to be the top canonical pathway." (PMID 33400740, 2020). "However, to the best of our knowledge, a direct modulatory role of TRIM25 in pyroptosis was not described in cancer cells." (PMID 39851496, 2025). "The clinical relevance of TRIM25 in cancers including HCC has not been previously investigated." (PMID 31953436, 2020). "Therefore, it is quite reasonable to speculate that as the regulator of TRIM25, the expression pattern of HBI-43 may also be sensitive to distinguish different cancer subtypes." (PMID 31052553, 2019). "Our study and previous report all showed that TRIM25 regulated both E-cadherin and TGF-β in different types of cancers, suggesting TRIM25 may promote cell migration and invasion through regulating E-cadherin and activating TGF-β signaling pathway, resulting in the regulation of EMT." (PMID 28620119, 2017). "Therefore, targeting of TRIM25 via dual inhibition of NONO, on the one hand by restoring caspase-2-dependent NONO cleavage and on the other hand by impeding K63-linkage-dependent NONO ubiquitination, might turn out as a valid strategy for novel cancer therapy." (PMID 39851496, 2025).
infectious (2 papers, 2022). "TRIM25 can promote the ubiquitination and degradation of VP3 of an infectious bursal disease virus to inhibit virus replication." (PMID 35310411, 2022).
bacterial infections (1 paper, 2022). "As an important member of the TRIM family, TRIM25 has been repeatedly reported to play important roles in mammalian immune responses to both viral and bacterial infections, which can induce the production of type I interferon and the upregulation of IFN-stimulated genes." (PMID 36360326, 2022).
cardiovascular disease (1 paper, 2022). "However, the role of TRIM25 in cardiovascular disease remains unknown." (PMID 35871160, 2022).
genetic disorders (1 paper, 2022).
metabolic disorders (1 paper, 2018). "Taken together, these data indicate that TRIM25 is a novel E3 ubiquitin ligase of PPARγ and that TRIM25 is a novel target for PPARγ-associated metabolic diseases." (PMID 30323259, 2018).
TRIM25 also shares sentences with these, for which no sentence is quoted: Salmonella Infections (4 papers); cervical carcinoma (2); pancreatic cancer (2); prostate adenocarcinoma (2); atypical hemolytic-uremic syndrome (1); avian influenza (1); chronic myeloid leukemia (1); Intellectual disability (1); Intervertebral Disc Degeneration (1); leukaemia (1); lung adenocarcinoma (1); lymph node metastasis (1); lymphoma (1); meningitis (1); Merkel cell carcinoma (1); mesothelioma (1); microangiopathic hemolytic anemia (1); osteosarcoma (1); papillary thyroid cancers (1); parasitic infection (1); renal failure (1); spastic ataxia (1); stomach adenocarcinoma (1); Thrombocytopenia (1); type 2 diabetes (1); X-linked nephrogenic diabetes insipidus (1).